ADGRA1 (adhesion G protein-coupled receptor A1)
Description:
Orphan receptor.
Synonyms: GPR123; KIAA1828
Tractability: Antibody: UniProt predicts a signal peptide or a membrane-spanning region; its Gene Ontology location is reachable by antibodies, with medium confidence.
Target class: Family B G protein-coupled receptor; Membrane receptor
Gene: Protein-coding gene on chromosome 10 (133,087,924 to 133,131,675, forward strand). Ensembl gene ENSG00000197177.
Subcellular location: Membrane
Gene Ontology:
Molecular function: protein binding; G protein-coupled receptor activity; transmembrane signaling receptor activity
Biological process: cell surface receptor signaling pathway; G protein-coupled receptor signaling pathway; signal transduction
Cellular component: glutamatergic synapse; membrane; plasma membrane; postsynaptic density
Genetic constraint (gnomAD): Loss-of-function variants: 12 observed, 18.96 expected, observed/expected ratio (o/e) 0.63, 90% interval 0.41 to 1.02. The upper end of that interval is the gene's LOEUF score, 1.02, which puts it in group 4 of 6, group 1 being the genes least tolerant of losing a copy. Missense variants: 788 observed, 715.01 expected, observed/expected ratio (o/e) 1.1, 90% interval 1.04 to 1.17. Synonymous variants: 384 observed, 325.42 expected, observed/expected ratio (o/e) 1.18, 90% interval 1.09 to 1.28.
Homologues: Orthologues: chimpanzee ADGRA1 (99% identical), macaque ADGRA1 (96% identical), guinea pig ADGRA1 (83% identical), mouse Adgra1 (82% identical), dog ADGRA1 (82% identical), pig ADGRA1 (81% identical), rat Adgra1 (67% identical), tropical clawed frog adgra1 (65% identical), rabbit ADGRA1 (59% identical). Paralogues in human: ADGRA3 (42% identical), ADGRA2 (40% identical), ADGRB1 (16% identical), ADGRB2 (16% identical), ADGRB3 (15% identical), ADGRG6 (15% identical), ADGRG2 (15% identical), ADGRL1 (15% identical), ADGRL3 (14% identical), ADGRL2 (14% identical), ADGRF5 (13% identical), ADGRG4 (13% identical), and 30 more.
Diseases named in the same sentence as ADGRA1 in open-access papers:
ADGRA1 is named in the same sentence as 11 diseases in open-access papers, as found by Europe PMC text mining. Sharing a sentence is not in itself a finding about the gene and the disease. The quoted sentences say what the papers report.
prediabetes (2 papers, 2022 to 2025). "ADGRA1 gene was associated with prediabetes status change in the current analysis." (PMID 35769078, 2022). "Our study provided the first evidence that the ADGRA1 gene is involved in prediabetes status change." (PMID 35769078, 2022).
depression (1 paper, 2019). "Moreover, GPCRs (including ADGRA1, ADGRV1, CELSR2, and S1PR5) previously reported to be implicated in the physiopathology and pharmacology of depression were also significantly altered." (PMID 30983951, 2019).
hyperthyroidism (1 paper, 2021). Overactivity of the thyroid gland resulting in overproduction of thyroid hormone and increased metabolic rate. "All above, Adgra1−/− male mice exhibit mild central hyperthyroidism." (PMID 33824276, 2021).
uterine corpus endometrial carcinoma (1 paper, 2025). A endometrial carcinoma (disease) that involves the body of uterus. "Correlation studies of ADGRs reveals that ADGRG3, ADGRA1, ADGRF1, CD4T cells and CD8 cells were involved in the tumor-related inflammatory response of uterine corpus endometrial carcinoma (UCEC) patients, and affected the clinical prognosis of UCEC patients." (PMID 40110435, 2025).
metabolic disorders (1 paper, 2021). "Modulation of Adgra1 signaling may uncover new therapeutic strategies to control thermogenesis and combat metabolic disorders." (PMID 33824276, 2021).
ADGRA1 also shares sentences with these, for which no sentence is quoted: tumor (3 papers); acute myeloid leukemia (1); allergic asthma (1); asthma (1); chronic myeloid leukemia (1); glioma (1).